SOX1 (SRY-box transcription factor 1)
Description:
Transcriptional activator. May function as a switch in neuronal development. Keeps neural cells undifferentiated by counteracting the activity of proneural proteins and suppresses neuronal differentiation (By similarity).
Tractability: No criterion of Open Targets' tractability assessment is met for any kind of drug.
Gene: Protein-coding gene on chromosome 13 (112,067,149 to 112,071,706, forward strand). Ensembl gene ENSG00000182968.
Subcellular location: Nucleus
Pathways (Reactome):
Developmental Biology: Formation of the anterior neural plate; Formation of the posterior neural plate
Gene Ontology:
Molecular function: protein binding; RNA polymerase II cis-regulatory region sequence-specific DNA binding; DNA binding; DNA-binding transcription activator activity, RNA polymerase II-specific; DNA-binding transcription factor activity; DNA-binding transcription factor activity, RNA polymerase II-specific; sequence-specific DNA binding
Biological process: brain development; chromatin organization; interneuron migration; negative regulation of transcription by RNA polymerase II; neuron differentiation; positive regulation of transcription by RNA polymerase II; regulation of DNA-templated transcription; regulation of oligodendrocyte differentiation
Cellular component: chromatin; nucleus
Genetic constraint (gnomAD): Loss-of-function variants: 2 observed, 0.71 expected, observed/expected ratio (o/e) 2.81. That is too few expected variants to judge how well the gene tolerates losing a copy. Missense variants: 376 observed, 302.21 expected, observed/expected ratio (o/e) 1.24, 90% interval 1.14 to 1.36. Synonymous variants: 267 observed, 152.32 expected, observed/expected ratio (o/e) 1.75, 90% interval 1.59 to 1.92.
Homologues: Orthologues: chimpanzee SOX1 (100% identical), mouse Sox1 (99% identical), rat Sox1 (99% identical), pig SOX1 (98% identical), rabbit SOX1 (95% identical), tropical clawed frog sox1 (77% identical), zebrafish sox1b (71% identical), zebrafish sox1a (70% identical), Drosophila melanogaster SoxN (43% identical). Paralogues in human: SOX3 (55% identical), SOX2 (51% identical), SOX21 (31% identical), SOX14 (29% identical), SOX15 (28% identical), SOX7 (22% identical), SOX17 (22% identical), SOX10 (21% identical), SOX18 (21% identical), SOX8 (21% identical), SOX11 (20% identical), SOX9 (20% identical), and 8 more.
Diseases named in the same sentence as SOX1 in open-access papers:
SOX1 is named in the same sentence as 110 diseases in open-access papers, as found by Europe PMC text mining. Sharing a sentence is not in itself a finding about the gene and the disease. The quoted sentences say what the papers report.
cervical carcinoma (29 papers, 2012 to 2026). A carcinoma arising from either the exocervical squamous epithelium or the endocervical glandular epithelium. "Although the methylation of SOX1 have been found to be associated with genitourinary tumors, including cervical cancer, prostate cancer and ovarian cancer, this is the first time that methylation of SOX1 has been found in NSCLC." (PMID 23599765, 2013). "Pooled results for the association of SOX1 promoter hypermethylation with cervical cancer risk." (PMID 32849763, 2020). "Diagnostic value of 19 CpG sites of SOX1 promoter for cervical cancer." (PMID 32849763, 2020). "SOX1 inhibits the progression of hepatocellular carcinoma, cervical cancer, nasopharyngeal carcinoma and lung cancer." (PMID 39889187, 2025). "Single methylation of LOC100289333 (LOC100289333m), ZIC1 (ZIC1m) and SOX1 (SOX1m) tested positive in all cervical cancer scrapings." (PMID 38031140, 2023). "SOX1 is hypermethylated in cervical cancer, ovarian cancer, and HCC according to our previous studies." (PMID 37190139, 2023). "Our previous data showed that SOX1 was hypermethylated in several cancers, including cervical cancer, ovarian cancer, and HCC." (PMID 37190139, 2023). "After sorting the data, we selected MEG3, TIMP3, DAPK1, and SOX1 as being the most hypermethylated genes specific for the incipient stages of cervical carcinoma, while MLH1 and MALAT1 were chosen as the most hypomethylated genes." (PMID 35682732, 2022). "Previous studies have discovered that many genes in the SOX family participate in carcinogenesis, such as SOX1, which can affect the growth and invasion of cancer cells in cervical cancer, breast cancer, lung cancer, glioblastoma and nasopharyngeal cancer." (PMID 34098886, 2021). "At present, many studies explored the correlation between SOX1 gene promoter and cervical cancer and SILs, but the research results are inconsistent." (PMID 32849763, 2020). "Previously, in addition to identifying DNA methylation biomarkers, we also revealed that LMX1A and SOX1 were tumor suppressor genes in cervical cancer and hepatocellular carcinoma." (PMID 31547144, 2019). "QMSP was designed for 5 genes (GFRA1, SLC6A5, SOX1, SOX14, TBX20) and their diagnostic potential was evaluated on scrapings from a large series of cervical cancer patients (n=125: 57 ADC and 68 SCC) and controls with similar age." (PMID 27738327, 2016). "A recent study showed that SOX1 can be a tumor suppressor partly through the Wnt/β-catenin signaling pathway in cervical cancer." (PMID 26057869, 2015). "The study showed that SOX1 might be a tumor suppressor in cervical cancer partly through the Wnt/β-catenin signaling pathway." (PMID 38031140, 2023). "In addition, many studies have shown that SOX1 can be used as a biomarker for a variety of tumors, such as cervical cancer, colon cancer, glioma, liver cancer, ovarian cancer, and small cell lung cancer." (PMID 34876142, 2021). "Furthermore, SOX1 was identified as a tumor suppressor gene, because it interfered with Wnt/β-catenin signaling in cervical cancer cells and hepatocellular carcinoma." (PMID 27738327, 2016). "Of the 53 differentially methylated candidates that were found in both ADC and SCC, 20 genes were described previously in literature as being more frequently methylated in cancer, and 6 genes in (squamous-cell) cervical cancer (SOX1, SOX14, ONECUT1 and WT1) or high-grade CIN (GFRA1, SOX1 and TBX20)." (PMID 27738327, 2016). "Overexpression of E6 / E7, p16 /ki-67, miR-9, SCC-Ag, M-CSF, VEGF proteins, or JAM3, SOX1, and L1 genes following infection with HPV can be detected based on their elevated levels in plasma, serum, Cervical scraping, or tissue as predictors of increased risk of cervical cancer progression." (PMID 33292364, 2020). "The use of differential methylation hybridization using a pilot methylation array allowed the identification of SOX1, NKX6-1, PAX1, WT1, and LMX1A as frequently methylated genes in cervical cancer and precursor lesions." (PMID 34790573, 2021).
cervical carcinoma (continued). "In further studies, it will be essential to analyze the correlation between SOX1 and PAX1 methylation status and sensitivity of the cervical cancer cell to radiotherapy and chemotherapy." (PMID 33376722, 2020). "In previous studies, we discovered that SOX1, NKX6-1, PAX1, WT1, and LMX1A are highly methylated in cervical cancer." (PMID 22815913, 2012). "The differential methylation hybridization (DMH) using a pilot methylation array identified SOX1, NKX6-1, PAX1, WT1, and LMX1A as frequently methylated genes in cervical cancer and its precursor lesions." (PMID 22815913, 2012). "Also, SOX1 increases the expression of CDH1, leading to the suppression of cell growth and invasiveness of cervical cancer." (PMID 38675711, 2024). "Furthermore, we recently demonstrated that SOX1 acts as a tumor suppressor by interfering with the Wnt/β-catenin signaling pathway in HCC and cervical cancer." (PMID 37190139, 2023). "Overexpression of SOX1 could inhibit cell proliferation, invasion, and tumor formation in most cancer types, such as NPC, hepatocellular carcinoma, cervical cancer, lung cancer, gastric cancer, breast cancer and cholangiocarcinoma." (PMID 37369660, 2023). "Furthermore, aberrant methylation of SOX genes in cancer has been frequently reported; for instance, SOX1 and SOX11 present hypermethylation in cervical cancer and endometrial cancer, respectively." (PMID 34098886, 2021). "SOX1 and SOX14 are methylation biomarkers applicable for screening of all cervical cancer types." (PMID 27738327, 2016). "DNA methylation analysis of SOX1 and POU4F3 in cervical scrapings consistently detects cervical cancer and the majority of CIN3 lesions, and has the capacity to broaden its use on cervical scrapings through the detection of a substantial subset of complex hyperplasia." (PMID 26057869, 2015). "Various host cell methylated genes such as SOX1, PAX1, JAM3, EPB41L3, CADM1, and MAL have been investigated for predicting cervical lesions, with PAX1 gene methylation showing the most significant correlation with the progression of cervical intraepithelial neoplasia and cervical cancer occurrence." (PMID 39155349, 2024). "Studies have shown that SOX1 can inhibit the occurrence and development of HCC, esophageal cancer, nasopharyngeal carcinoma, lung cancer, and cervical cancer; however, its role in CCA has not been reported." (PMID 34876142, 2021). "Compared to the gene panels recently reported by our group the combination of SOX1/SOX14 methylation showed less positive test results, both in scrapings from women without cervical disease and in women with high-grade CIN, but not in women with cervical cancer." (PMID 27738327, 2016).
glioma (16 papers, 2011 to 2025). A benign or malignant brain and spinal cord tumor that arises from glial cells (astrocytes, oligodendrocytes, ependymal cells). "SOX1 has been implicated with glioma, while SOX2 has been depicted as unfavorable prognostic marker." (PMID 33639927, 2021). "In summary, SOX1 genetic silencing induces a strong tumor suppressor phenotype in glioma cells associated with impaired self-renewal, proliferation, tumor initiation and progression." (PMID 28425506, 2017). "The redundancy between members of the SOXB1 subgroup enhances their interactions with other genes involved in the renewal and proliferation of glioma stem cells (SOX1, SOX2, and SOX3)/Cdks/cyclins." (PMID 35392088, 2022). "Expression of SOX1 in human glioma is heterogeneous with high expression of SOX1 conferring poor prognosis." (PMID 34012965, 2021). "Inhibition of SOX1 in glioma cells leads to decreased proliferation, self-renewal, and reduced capacity to grow in vivo." (PMID 34012965, 2021). "We studied the levels of SOX1 expression in four independent GSC cultures detecting markedly higher levels in GSCs than the conventional glioma cell lines." (PMID 28425506, 2017). "In summary, these results identify a functional role for SOX1 in regulating glioma cell heterogeneity and plasticity, and suggest SOX1 as a potential target in the GSC population in glioblastoma." (PMID 28425506, 2017). "In summary, our results firmly establish that SOX1 behaves as an oncogene in glioblastoma regulating glioma cell plasticity." (PMID 28425506, 2017). "Next, we studied the role of SOX1 in glioma cell activity through knockdown and overexpression assays." (PMID 28425506, 2017). "Commonly, the transcription factor SOX1 is downregulated in cancer due to promoter hypermethylation, however, the inhibition of SOX1 in glioma stem cells has been found to decrease proliferation in vitro, while overexpression of SOX1 suppresses invasion and growth in lung cancer." (PMID 40170512, 2025). "On the other hand, patients with high levels of SOX1 in lower grade glioma had better outcomes." (PMID 37369660, 2023). "Similarly, histones H3K9 and H3K4 acetylation and DNA methylation have been reported to be involved in GDNF and SOX1 overexpression in gliomas." (PMID 35392088, 2022). "For example, knockdown of SOX1 expression in glioma stem cells has been found to impair the self-renewal, proliferation, viability, and tumorigenesis ability of glioma cells, while the overexpression of SOX1 promoted the malignant phenotype of glioma." (PMID 36524115, 2022). "Interestingly, the upregulation of SOX1 is involved in glioma malignancy and proliferation, but the mechanism involved in this process is not well defined." (PMID 34513834, 2021). "We further evaluated the role of SOX1 silencing in glioma cells." (PMID 28425506, 2017). "Since SOX1 acts as a tumor suppressor in different types of cancer through the Wnt/β-catenin signaling pathway (see introduction), we examined the activity of this pathway after silencing of SOX1 in glioma cells and GSCs." (PMID 28425506, 2017). "First, we compared the expression of SOX1 in human low-grade glioma and normal brain samples." (PMID 28425506, 2017). "Interestingly, oncospheres derived from all five glioma cell lines had higher levels of SOX1 than observed in adherent cells." (PMID 28425506, 2017). "Thus, similar to the healthy CNS undifferentiated proliferating cells in high grade gliomas co-express Sox1-3 transcription factors." (PMID 21483788, 2011). "Indeed, POU3F2, SOX2, SALL2, and OLIG2 have been shown to be the core set of transcription factors essential for GBM propagation, which are within the set of 19 transcription factors (including SOX1) required for successful reprogramming of differentiated glioma cells into GSCs48." (PMID 28425506, 2017).
glioma (continued). "Functional analyses also revealed a strong inverse correlation between the expression of PR-LncRNAs and SOX family members (SOX1, SOX2, and SOX9) in glioma clinical biopsies and glioma cells." (PMID 37047365, 2023). "TFBS for factors such as ZNF85, PO3F1, HX36, SOX1, and SOX10 were found in genes overexpressed in GII gliomas." (PMID 36850002, 2023). "Almost all SOX genes, for instance, SOX1, SOX2, SOX7, and SOX10, have been found to have the potential to regulate the progression of glioma, whose expression levels are also related to the prognosis of patients." (PMID 36524115, 2022). "The markers were glioma stem cell markers (CD133 and Msh1), neuronal lineage markers (nestin, sox1, sox2, and pax6), and differentiated markers (GFAP, Tuj1, and Olig123)." (PMID 33575478, 2021). "Mechanistically, we found an inverse correlation between PR-LncRNA expression and SOX1, SOX2 and SOX9 stem cell factors in human glioma biopsies and in glioma cells in vitro." (PMID 30143669, 2018). "SOX1 expression was low in Sall2 KO cells during neural differentiation, and SALL2 was one of the factors that can reprogram differentiated glioma cells into glioma stem cells." (PMID 39349437, 2024). "The possible interaction between TGF-β (GDNF) and SOXB1 (SOX1, SOX2, SOX3) family members might explain the difficulties in regulating glioma stem cell recurrence after surgical tumor resection and drug resistance." (PMID 35392088, 2022). "Taking together, SOX2 could act through SOX1 and SOX18, and thus play roles in both maintaining stem cell properties of glioma cells and forming tumor vasculature in gliomas, which are two major obstacles preventing us from treating these tumors effectively." (PMID 21211035, 2011). "Interestingly, we observed that specially SOX1 and SOX2 expression was elevated in those cells, suggesting that these members of the SOX family may be mediators of PR-LncRNA activity in gliomas." (PMID 30143669, 2018). "Moreover, experiments in vitro revealed that their levels, especially of SOX1 and SOX2, were significantly elevated in PR-LncRNA silencing cells and that knock-down of SOX1 and SOX9 expression dramatically reduced the pro-oncogenic activities promoted by PR-LncRNA silencing in glioma cells." (PMID 30143669, 2018).
small cell lung carcinoma (14 papers, 2007 to 2025). Small cell lung cancer (SCLC) is a highly aggressive malignant neoplasm, accounting for 10-15% of lung cancer cases, characterized byrapid growth, and early metastasis. "It has been indicated in previous reports that antibody against SOX1 is a paraneoplastic high-risk factor antibody that showed more than 70% frequency associated with cancer, and the most commonly associated cancer type with SOX1 is small cell lung cancer." (PMID 36009116, 2022). "Anti-SOX1 antibodies were highly associated with small cell lung cancer." (PMID 34056010, 2021). "Imaging and cerebrospinal fluid analysis confirmed paraneoplastic limbic encephalitis associated with small-cell lung carcinoma (SCLC), and serum analysis revealed strongly positive anti-SOX1 antibodies." (PMID 41394839, 2025). "Patients with overlapping SOX1 antibodies have progressive ophthalmoplegia and cerebellar ataxia symptoms, alongside small cell lung cancer." (PMID 40028323, 2025). "Another patient, a 42-year-old male positive for anti-GABABR, GAD65, Ma2, and SOX1 antibodies, was diagnosed with small cell lung cancer and treated with IVIg, ASMs, and platinum-based chemotherapy, dying 1 year after diagnosis." (PMID 39539648, 2024). "Anti-SOX1 antibodies are regarded as serum biomarkers for small cell lung cancer." (PMID 40028323, 2025). "However, many authors have pointed out that anti-SOX1 antibodies are oftentimes associated with a paraneoplastic form of Lambert-Eaton Myasthenic Syndrome (LEMS) and Small Cell Lung Cancer (SCLC)." (PMID 36324062, 2022). "Seropositive SOX‐1 antibodies are support for the diagnosis of LEMS and have high specificity for small cell lung cancer (SCLC)." (PMID 38497229, 2024). "It has been reported that SOX1 antibodies are common in the serum of patients with small cell lung carcinoma (SCLC) and may be serve as specific serological markers." (PMID 23599765, 2013). "Further screening of these patients revealed four cases with tumors: three young females had ovarian teratomas (two were anti-NMDAR positive; one was positive for both anti-NMDAR and mGluR5), and one 45-year-old male had small cell lung cancer (positive for anti-GABABR, GAD65, SOX1, and Ma2)." (PMID 39539648, 2024). "Thus, SOX1, SOX2, SOX3 and SOX21 as well as SOX4 were demonstrated to elicit humoral immune responses in small cell lung cancer patients." (PMID 17375044, 2007).